CD4 (CD4 molecule)
Diseases named in the same sentence as CD4 in open-access papers (continued):
Sharing a sentence is not in itself a finding about the gene and the disease.
type 1 diabetes (continued). "We show that type 1 diabetics (T1D) have a Treg activation defect through an increase in resting Tregs (rTregs, CD4+CD25+Foxp3+CD45RA) and decrease in aTregs (CD4+CD25+Foxp3+CD45RO) (n= 55 T1D, n=45 controls, P=0.01)." (PMID 26900470, 2016). "In type I diabetes (T1D), CD8+ T cells, CD4+ T cells, B lymphocytes, and other plasma cells appear to be involved in the destruction of the pancreatic insulin-producing β cells, together with a poor immune regulation." (PMID 27635405, 2016). "We also report the use of CD4+ T cell converted antigen-specific DN T cells in combination with ATS to suppress and reverse autoimmune diabetes in NOD mice with newly developed type 1 diabetes." (PMID 26911290, 2016). "The present study of histone acetylation in type 1 diabetes patients chose lymphocytes or monocytes, but CD4+ T lymphocytes play a central role in the pathogenesis of LADA, choosing CD4+ T lymphocytes to study is more direct and deep." (PMID 26839444, 2015). "High-grade islet infiltration by CD4- and CD8-positive T cells and macrophages was observed in a patient with recent-onset type 1 diabetes." (PMID 25338552, 2015). "On the other hand, exposure to 1,25(OH)2D3 or TX527 decreased the expression of CLA on CD4+ and CD8+ T cells from both control subjects and type 1 diabetes patients." (PMID 25279717, 2014). "On day 8, both 1,25(OH)2D3 and TX527 had induced CCR10 on CD4+ and CD8+ T cells, not only from control donors, but also from patients with type 1 diabetes." (PMID 25279717, 2014). "In transgenic mice, the overexpression of CXCL10 in the pancreas induces a rapid recruitment of effector CD4+ and CD8+ T cells and accelerates the progression of type I diabetes." (PMID 24586509, 2014). "We and others have shown that PD1-PDL1 interaction is critical for the regulation of CD4 and CD8 autoreactive T cells involved in the development of type 1 diabetes." (PMID 24586872, 2014). "In line with previous findings, we have confirmed normal CD4+/CD8+ T cell ratios and the Treg frequencies in our type 1 diabetes patient cohort." (PMID 25279717, 2014). "Supporting this finding, elevated numbers of CD4+CD25highCD127low T cells in cultures of 1,25(OH)2D3- or TX527-treated T cells from patients with type 1 diabetes were detected, thereby confirming the increased presence of Tregs after cytokine exposure." (PMID 25279717, 2014). "We have recently reported that NOD Stat5b transgenic mice have significantly lower incidence of type 1 diabetes than NOD mice and the levels of CD4+ regulatory T cells are increased in the Stat5b transgenic NOD mice." (PMID 23457589, 2013). "Type 1 diabetes mellitus (T1DM) is characterized by autoimmune destruction of insulin-producing beta cells of pancreatic islets by CD4+ cytotoxic T lymphocytes with the contribution of CD8+ helper T lymphocytes, which leads to permanent impairment of glucose metabolism." (PMID 23936838, 2013). "In type 1 diabetes (T1D), CD8+ cytotoxic T lymphocytes, in conjunction with CD4+ T helper cells, destroy the insulin-producing β cells within the pancreatic islets of Langerhans." (PMID 22693523, 2012). "Other studies elucidated the role of CD8+ Tregs in Type 1 Diabetes and showed a regulatory activity of CD8+ Tregs on autologous, antigen-reactive CD4+ T cells in a cell contact-dependent manner." (PMID 23133648, 2012). "Defective development or depletion of Treg in animals, such as the naturally arising Foxp3+CD4+CD25+ Treg (nTreg), results in the development of autoimmune diseases, including type 1 diabetes (T1D)." (PMID 19924236, 2009). "Moreover, a recent study investigating gene expression in CD4+ and CD8+ T cells, natural killer (NK) cells, and B cells using RNA-seq found that gene expression differences in children progressing to type 1 diabetes were largely confined to CD4+ T cells." (PMID 41462339, 2025).
type 1 diabetes (continued). "Helminth infection with Heligmosomoides polygyrus prevents type 1 diabetes (T1D) in nonobese diabetic mice by enhancing IL-10 production from CD4(+) T cells, with protection lasting up to 40 weeks." (PMID 40299229, 2025). "CD4+ T lymphocytes were isolated from peripheral blood mononuclear cells (PBMCs) from male and female individuals at the onset of type 1 diabetes and from non-diabetic individuals, RNA was extracted and mRNA expression was analysed by real-time PCR." (PMID 38864887, 2024). "Furthermore, PNMA8A/PNMAL1 was listed among the candidate genes for stroke, as well as among cytotoxicity-related genes in CD4+ and CD8+ T cells that mark progression to type 1 diabetes." (PMID 38674024, 2024). "Our EU-tagging technique led to the identification of several tRFs delivered to beta cells upon adoptive transfer of activated CD4+/CD25− T cells from NOD.BDC 2.5 mice, a treatment known to trigger type 1 diabetes in the receiving NOD.SCID mice within a few days." (PMID 38967669, 2024). "Type 1 diabetes (T1DM), which can manifest at any age and accounts for 10 to 15% of all diabetes cases, is characterized by autoimmune processes involving islet-specific auto-reactive CD4+ and CD8+ T lymphocytes." (PMID 38313182, 2023). "Specifically, MOTS-c promoted the differentiation of CD4+CD25+FOXP3+ regulatory T cells (Tregs), which exhibited low glycolytic activity and showed therapeutic potential in type 1 diabetes (T1D) and other autoimmune diseases, through direct inhibition of mTOR complex 1 (mTORC1) signaling in T cells." (PMID 36670507, 2023). "This indicates that deamidation of C-peptide does not create a neoepitope that stimulates CD4+ T-cell proliferation in people without type 1 diabetes." (PMID 36619657, 2023). "In addition, we showed that in the group of patients with type 1 diabetes with anti-EBNA-1 antibodies in the IgG class, the percentage of CD3+CD4+IL-10+ T cells was significantly higher (p = 0.033)." (PMID 36768715, 2023). "Notably, inflammatory diseases including coeliac disease and type 1 diabetes (T1D) have a CD8 T cell-mediated disease component, but also involve CD4 T cells and B cells." (PMID 36200950, 2022). "To note, this aspect would be even more relevant if we wanted to extend this investigation to CD4+ T cell repertoire, bearing in mind that CD4+ TCR degeneracy is more pronounced than in CD8+ T cells, and trans-spliced peptides are under the spotlight in type 1 Diabetes." (PMID 33717099, 2021). "Likewise, patients with type 1 diabetes and the PDCD1 804C > T SNP have a significantly lower fraction of PD-1 expression in peripheral CD4+ T cells, which supports the observed trend." (PMID 33803602, 2021). "In an experiment in which anti-CD20 antibodies depleted B cells in NOD mice, MDSC amplified, inhibited the function of CD4+ and CD8+T cells through cell-to-cell contact and released IL-10 and NO, ultimately inhibiting the development of type 1 diabetes in mice." (PMID 34975496, 2021). "While we observed that expression of CD226 on both CD4+ and CD8+ T cells increased the frequency of type 1 diabetes incidence, we did not detect any changes in the thymic development or peripheral activation of CD4+ T cells in the absence of CD226." (PMID 33013915, 2020). "In our study we showed that the combination of an immunomodulatory agent such as the non-depleting anti-CD4 antibody with AAV-based insulin gene therapy allowed increased therapeutic benefit also for Type 1 diabetes." (PMID 30514969, 2019). "One early report suggested that FOXP3+ Tregs (defined as CD4+CD25+ T cells) were decreased in frequency in individuals with type 1 diabetes (vs control individuals without diabetes)." (PMID 28770318, 2017). "For example, while CD4+ iNKT cells protected non-obese diabetic mice from developing type 1 diabetes, CD4− iNKT cells secreting IL-17 exacerbated the disease." (PMID 28912775, 2017).
type 1 diabetes (continued). "We report here an increased production of IL-21 and, to a lesser extent, IL-17, but not IFN-γ, in memory CD4+ T effector (Teff) cells from type 1 diabetes patients as compared with healthy controls." (PMID 25652388, 2015). "Type 1 diabetes mellitus does not occur without the participation of CD3+ T lymphocytes with either a CD4+ or CD8+ phenotype." (PMID 26606254, 2015). "For the infiltration of CD4+ and CD8+ T lymphocyte, B lymphocytes, natural killer cells, dendritic cells and other immune cells take part in the damage of pancreatic β cells, which ultimately lead to type 1 diabetes." (PMID 24629100, 2014). "Adoptive transfer of type 1 diabetes to NOD-SCID recipients by diabetogenic CD4+ T-cells (inducer cells) can be prevented by B- but not T-cells (test cells) from donors immunized with scFvs if the specificity of the scFv and the inducer cell are matched." (PMID 23894487, 2013). "In mice and humans, susceptibility to type 1 diabetes is predominantly controlled by the classical MHC class II loci responsible for positive and negative selection of CD4+ T cell clones during thymic development." (PMID 23418596, 2013). "In this view, decreased effector CD4+ T cell functions and increased regulatory CD4+ T cell functions were observed following treatment of NOD mice (model for type I diabetes) with the B-cell maturation antigen (BCMA)-Fc construct, which blocks BLyS-mediated survival signals for B cells." (PMID 22461837, 2012). "Our results showed that IRF4 expression was up-regulated in NOD mice and correlated with the increased levels of CD4+CD8α− DCs, suggesting that IRF4 may be involved in abnormal DC functions in type 1 diabetes in NOD mice." (PMID 21647406, 2011). "Type 1 diabetes (T1DM) is an autoimmune disease through which the patient's immune system loses the immunologic tolerance against β cells antigens, resulting in an immune response against the islets which involves CD8+ and CD4+ cells." (PMID 19825196, 2009). "Moreover, in type 1 diabetes mice, when Treg cells are depleted, the level of IL-2 increases, but CD4 + T cells that secrete IL-2 do not increase." (PMID 37391717, 2023). "Based on the conducted analyses, no relevant differences were found in the percentage of CD3+CD4+ lymphocytes with intracellular expression of the selected cytokines in the patients with type 1 diabetes in relation to the presence of anti-VCA antibodies in the IgG class." (PMID 36768715, 2023). "Additionally, studies have challenged the stereotypical perspective that T2D is solely a metabolic disease and identified an autoimmunity component of T2D that overlaps with type 1 diabetes (T1D), i.e., increased β cell apoptosis triggered by the activation of T cells (CD8+ and CD4+)." (PMID 36066975, 2022). "However, in patients with type 1 diabetes, CD24hiCD38hi B cells failed to reduce IFNγ, TNFα and IL-17 production from CD4+ T cells." (PMID 34616408, 2021). "In addition, depletion of Treg cells led to an increase in IL-2 levels in mice with type 1 diabetes, but the numbers of CD4+ T cells that secreted IL-2 did not increase significantly." (PMID 33013198, 2020). "CD4+ T cells might, however, not be the only T cell subset relevant to type 1 diabetes pathogenesis." (PMID 26973647, 2016). "Indeed, assessment of surface expression of CD25 and CD127 on CD4+ T cells by flow cytometry showed that 1,25(OH)2D3 and TX527 increased the frequency of CD4+CD25highCD127low T cells in cultures of human T cells from patients with type 1 diabetes." (PMID 25279717, 2014). "Using this strategy, we were able to demonstrate the presence of islet-antigen-specific CD4+ and CD8+ T cells in Type 1 diabetes (T1D) patients under immunosuppressive treatments after allogeneic islet transplantation." (PMID 23390544, 2013).
type 1 diabetes (continued). "However, since IL6ST expression in CD4+ and CD8+ naive or central memory T cells co-localised with type 1 diabetes and IL6R expression did not, it is tempting to speculate that trans-signalling might be more important than classic IL-6 signalling in the pathogenesis of type 1 diabetes." (PMID 39271518, 2024). "While Th40 cells are present in non-autoimmune strains (up to 25%), they expand to about 60% of the CD4 compartment in non-obese diabetic (NOD) mice, a model of type I diabetes (T1D) and, coincidentally, a model for relapsing-remitting EAE." (PMID 28192476, 2017). "Type 1 diabetes features a lifelong Treg cell defect; namely, by an increase in resting Tregs (rTregs, or CD4 + CD25 + Foxp3 + CD45RO) and a paucity of activated Tregs (aTregs, or CD4 + CD25 + Foxp3 + CD45RA) compared to nondiabetic controls." (PMID 40869160, 2025). "Additionally, in type 1 diabetes (T1D), the presence of a disulfide bond on the A-chain of insulin enables the recognition by HLADR4+ CD4+ T-cells clones in patients, but not in healthy subjects." (PMID 35740078, 2022). "However, apart from an early report on vaccination with heat shock protein 60 specific CD4+ T-cells in NOD mice, this vaccination approach has to date not been applied to type 1 diabetes." (PMID 23894487, 2013).
Hypertension (306 papers, 2010 to 2026). The presence of chronic increased pressure in the systemic arterial system. "The drug α2 adrenoceptor agonists used in the treatment of hypertension can mediate the function of tumor-associated macrophages and CD4( +) T cells so that hypertensive patients with a history of related treatment can better benefit from immunotherapy." (PMID 38671373, 2024). "Regarding HIV-related factors, our study found that recent elevated CD4+ cell counts was associated with an increased risk of hypertension." (PMID 37025998, 2023). "Low CD4+ cell counts have been associated with higher risks for hypertension in PLWH, which disagrees with our findings." (PMID 37025998, 2023). "Coronary atherosclerosis was associated with male gender, older age, dyslipidemia, hypertension, lower CD4:CD8 ratio, lower HDL cholesterol, and higher triglyceride." (PMID 36827291, 2023). "This present 1:1 matched case-control study was conducted to analyze the association among dietary pattern, CD4+ T cells and hypertension." (PMID 36678161, 2023). "An adaptive response of CD4+ T cells has been implicated in hypertension and its complications, including atherosclerosis-based cardiovascular diseases." (PMID 35053985, 2022). "Of interest, CD4 + CD28nullTang cells, more prevalent in our RA cohort, have been associated with atherosclerotic risk in patients with hypertension." (PMID 36280849, 2022). "We have shown that PIBF improves inflammatory cytokines and decreases NK cell activation and CD4+ T cells in association with lowered ET-1 and sFLT-1 and, thus, hypertension in RUPP rats." (PMID 34831040, 2021). "Taken together, these results suggest CD8+ CD28null T-cells are associated with the development of hypertension and CD4+ CD28null cells engage in the pathogenic inflammation in hypertension." (PMID 34680058, 2021). "IL-23 acts as a stimulator and regulator for activating pathogenic Th17 lymphocytes, which induces hypertension only in SS rats through increasing the population of CD4+IL-17A+ (Th17) cells and the level of serum IL-17A." (PMID 32179549, 2020). "In adults, older age was associated with highertotal WMH volume, and age, hypertension and lower CD4+ T-lymphocytenadir with a higher number of periventricular WMH." (PMID 33112914, 2020). "A CD4 count ≤200 cells/mm3 was associated with significantly lower rates of hypertension, as compared to participants with a CD4 >200 cells/mm3." (PMID 30735518, 2019). "Ang II‐dependent hypertension was associated with an increased number of CCR5 positive (both CD4+ and CD8+) T‐cells in pVAT." (PMID 30658013, 2019). "Hypotension is associated with advanced HIV infection, and a study of ART-naïve HIV-infected patients in Tanzania suggested that lower CD4 count and more advanced disease were associated with lower rates of hypertension." (PMID 30735518, 2019). "Patients with interatrial block had a lower nadir lymphocyte CD4 count (124 vs 198 cells, p = 0.02) while advanced interatrial blocks were associated to older age (62.16 vs. 54.95 years, p = 0.046) and hypertension (77.8% vs. 32.3%, p = 0.009)." (PMID 31622385, 2019). "Interleukin (IL)-17A, interferon (IFN)-γ, and higher CD4+ T cell counts were associated with hypertension in ART-treated participants." (PMID 31165257, 2019). "After adjusting for age and anxiety, CD4 count ≤200 cells/mm3 was found to be associated with 44% lower odds of hypertension compared to CD4 >200 cells/mm3 (aOR = 0.56, 95% CI: 0.38, 0.83, p = 0.004)." (PMID 30735518, 2019). "Multivariable analyses among HIV-positive adults suggest that age, anxiety, and CD4 count are independently associated with hypertension." (PMID 30735518, 2019). "Mice with Nox2 deficiency in CD4+ T cells showed inhibition of Ang II–induced hypertension and cardiac remodeling due to increased Treg and reduction in Th17 content." (PMID 31321561, 2019).